FOXO1 (forkhead box O1)
Diseases named in the same sentence as FOXO1 in open-access papers (continued):
Sharing a sentence is not in itself a finding about the gene and the disease.
tumor (continued). "Higher levels of both H3K4me3 and H3K9Ac active chromatin marks are observed in U23674 and U21459 cells compared with U29415 and U31425 tumor cells, correlating with high versus low Pax3:Foxo1 expression, respectively." (PMID 25030697, 2014). "For U23674 tumor cells of the Myf6Cre myoblast lineage, a decrease in both Pax7 and Pax3:Foxo1 mRNA levels upon treatment with all of the drugs was observed, but the effect was more pronounced for HDAC inhibitors." (PMID 25030697, 2014). "At the level of histone marks, we observed a different chromatin state of the Pax3:Foxo1 locus in primary tumor cell cultures with different lineages of origin." (PMID 25030697, 2014). "FOXO1 is also known as a tumor suppressor and its deregulation has been identified in various tumors." (PMID 25472505, 2014). "Taken together, our results imply that FOXO1 acts as a tumor suppressor in ES, and identify FOXO1 reactivation as a promising strategy for a future ES-specific therapy." (PMID 23995784, 2014). "In an orthotopic xenograft mouse model, MSA increased FOXO1 expression in the tumor paralleled by a significant decrease in ES tumor growth." (PMID 23995784, 2014). "RT–PCR studies also showed higher levels of Pax3:Foxo1 mRNA levels in murine primary tumor cell cultures derived from Myf6Cre,Pax3(P3Fa/P3Fa) tumors (green) compared with primary tumor cell cultures from Pax7CreER,Pax3(P3Fa/P3Fa) tumors (U31425 and U28285)." (PMID 25030697, 2014). "In some cases FOXO3 has the opposite effect of enhancing survival of drug-resistant tumor cells through its antioxidant effect like that of FOXO1 in this process." (PMID 24864265, 2014). "In accordance with the expression levels of miR-182, there were reduced expressions of FOXO3 and FOXO1 in tumor vs. normal tissues in the SBU cohort." (PMID 24865442, 2014). "CDK1 and CDK2, two cell cycle regulatory protein kinases that play important roles in cell cycle transitions, have been reported to phosphorylate FOXO1 and attenuate its tumor suppressor function." (PMID 25472505, 2014). "We identified FOXO1 as a tumor suppressor in PMBL and revealed mechanisms responsible for its repression." (PMID 24977668, 2014). "FOXO1, a putative tumor suppressor, is also a target of miR-182 and an antisense inhibitor specific to miR-182 which leads to a significant increase in endogenous FOXO1 expression." (PMID 24260062, 2013). "Members of the major oncogenic cascades are significantly overrepresented among the predicted targets of the miRNAs, consistent with tumor-suppressive role of FOXO1." (PMID 23748164, 2013). "Previous studies found that FOXO1 promotes apoptosis in many cell types and is suggested as a tumor suppressor." (PMID 24205217, 2013). "FOXO1 is considered as a tumor repressor as it promotes cell-cycle arrest and apoptosis by regulating specific gene-expression programs." (PMID 23874926, 2013). "The Forkhead box O (FoxO) transcription factor FOXO1 is an important tumor suppressor involved in apoptosis, the cell cycle, DNA damage repair and oxidative stress." (PMID 23946796, 2013). "Down-regulation or inhibition of PAX3/FOXO1 inhibits proliferation and induces apoptosis in aRMS cells, hence the aRMS tumor cells become dependent on fusion protein expression." (PMID 23372815, 2013). "FOXO1 expression was significantly reduced in the tumor with expression being detectable in 62% of benign epithelial cells, but only in 31% of tumor cells." (PMID 24260486, 2013). "The Forkhead box O (FoxO) transcription factor FOXO1 is emerging as an important tumor suppressor that modulates the expression of genes involved in apoptosis, the cell cycle, DNA damage repair and oxidative stress." (PMID 23946796, 2013).
tumor (continued). "Suppression of FOXO down-regulates target genes, including Bim, FasL and TXNIP, a tumor suppressor gene, whereas overexpression of FOXO1 enhances TXNIP promoter activity." (PMID 24112473, 2013). "It is known that FoxO1 controls the tumor growth; the expression of FoxO1 inhibits the tumor growth and triggers the ultimate death of tumor." (PMID 22532866, 2012). "Deletion of all FOXO1, FOXO3, and FOXO4 alleles in adult mice induced a cancer prone phenotype, supporting a tumour suppressing function of these proteins." (PMID 22848740, 2012). "Forkhead box protein O1 (FOXO1), a key member of the FOXO family of transcription factors, acts as a tumor suppressor and has been associated with various key cellular functions, including cell growth, differentiation, apoptosis and angiogenesis." (PMID 23029264, 2012). "Wild type mice on CR diet showed lower incidence of tumor and tumor related deaths as compared to FOXO1 knockout heterozygous mice, thus suggesting FOXO as a mediator of CR anti-tumor effects as well." (PMID 22934068, 2012). "The results showed that either resveratrol or IL-2 treatment can induce the expression of FoxO1 in the tumor in vivo." (PMID 22532866, 2012). "Resveratrol-induced suppression of tumor growth in mice was associated with inhibition of ERK and PI3K/AKT pathway and activation of FOXO1 and FOXO3a." (PMID 21980390, 2011). "Resveratrol-induced suppression of PANC1 tumor growth in nude mice was associated with inhibition of ERK, PI3K, AKT, FOXO1 and FOXO3a phosphorylation, and induction of apoptosis in tumor tissues." (PMID 21980390, 2011). "This is the first report, to the best of our knowledge, to show a link between FOXO1 activation in cancer cells and tumor angiogenesis." (PMID 21696576, 2011). "Consequently, key proteins involved in tumor progression and metastasis, including p-Akt, p-Gab1, and FOXO1, were markedly inhibited in tumors from CDP-treated mice." (PMID 41683520, 2026). "However, the mechanism by which the transcription factor forkhead box protein O1 (FOXO1) regulates the proliferation and survival of malignant tumor cells under high levels of reactive oxygen species (ROS) remains poorly understood." (PMID 41124013, 2025). "Compared to the control group, the tumor significantly decreased phosphorylated Akt and FOXO1 levels while increasing phosphorylated NF-κB p65 expression, which represents the activation of FOXOs and NF-κB, respectively, in the gastrocnemius muscle (p < 0.01 or 0.001)." (PMID 40136406, 2025). "Downregulation of FOXO1 may promote methylation-mediated gene silencing, thereby accelerating tumor progression." (PMID 40396172, 2025). "FOXO1 is downregulated in HCC tumor tissues compared with normal liver tissues." (PMID 40075616, 2025). "Additionally, we demonstrate that Sirt1 plays a vital role in suppressing the transcriptional activity of FOXO1 through deacetylation, leading to decreased androgen secretion and ultimately suppressing tumor progression in GBM." (PMID 40075208, 2025). "Initial examination of these clusters/subsets revealed that all GEMM tumours in ML clusters corresponded to Pax3::Foxo1 in one of three lineages (Myf5, Myf6, and Pax3) while all tumours in MR1 corresponded to DNA alterations other than Pax3::Foxo1 in these same three lineages." (PMID 39812007, 2025). "Notably, Myf6Cre showed the highest tumor incidence, indicating that Pax3::Foxo1 expression in specific lineages can drive more aggressive tumor behavior." (PMID 40599857, 2025). "In tumor-bearing mice, Lipopolysaccharide-induced tumor necrosis factor alpha factor (LITAF) acts as a tumor suppressor gene, promoting FOXO-1 expression to inhibit SIRT1, thereby upregulating epithelial marker E-cadherin and downregulating mesenchymal marker N-cadherin." (PMID 40567502, 2025). "In mouse FN RMS tumours (with low or no Pax3::Foxo1), our study did not identify an association between other driver mutations and DNA methylation." (PMID 39812007, 2025).
tumor (continued). "Experimental studies in glioma models revealed that SIRT6 overexpression suppresses tumor growth by promoting histone deacetylation and cell-cycle arrest, whereas SIRT1 limits androgen biosynthesis through FOXO1 deacetylation, thereby restraining tumor progression." (PMID 41425553, 2025). "Finally, we validated the FOXO1 target by generating a reporter construct, and luciferase experiments also indicated that FOXO1 luciferase activity increased in T-DM1-treated tumor cells." (PMID 40925917, 2025). "Notably, UA upregulated Sirt1 and FOXO1 expressions in tumor tissues, reinforcing its role in modulating pathways critical to tumor suppression." (PMID 40568370, 2025). "FOXO1 transcriptionally regulates target genes involved in tumor cell apoptosis and proliferation." (PMID 41124013, 2025). "PAX3::FOXO1-target genes likely have diverse pro-tumorigenic functions such as stimulating proliferation and invasion, inhibiting differentiation, and promoting cancer cell survival by repressing tumor suppressors." (PMID 40599857, 2025). "Additionally, our study suggests that Sirt1 acts as a tumor suppressor by promoting the deacetylation of FOXO1." (PMID 40075208, 2025). "FOXO1, a member of the forkhead transcription factor family, is crucial in regulating cancer cell proliferation, apoptosis, and migration, functioning as a key tumor suppressor in various cancers." (PMID 41369154, 2025). "FOXO1, as a critical tumor suppressor, antagonizes the function of the epigenetic repressor EZH2." (PMID 40396172, 2025). "In this study, silencing FOXO1 increased tumor cell apoptosis under oxidative stress, while overexpressing FOXO1 improved the survival of cancer cells at high ROS levels, highlighting the role of FOXO1 in bolstering tumor cell antioxidative capacity and survival." (PMID 41124013, 2025). "In addition, GlcN increases the expression of FoxO1 and FoxO3, which play a crucial role as tumor suppressors in various cancers." (PMID 39816727, 2025). "Furthermore, we observed that all the tumours with weak expression of Pax3::Foxo1 were significantly enriched in the MR2 subset compared with the MR1 subset (p = 0.015)." (PMID 39812007, 2025). "Notably, in CD8+ memory T cells, FOXO1 activation supports T-cell maintenance and enhances anti-tumor immune surveillance." (PMID 41374004, 2025). "Specifically, FOXO1 and FOXO3a have context‐dependent oncogenic or tumor‐suppressive roles." (PMID 40751690, 2025). "Finally, tumours in MR2 corresponded to either Pax3::Foxo1 in the Pax7 lineage or DNA alterations other than Pax3::Foxo1 in one of three lineages (Myf6, Pax3, or Pax7)." (PMID 39812007, 2025). "Targeting FoxO1 could therefore represent a novel approach to enhance anti-tumor immune responses by reprogramming TAMs towards a more pro-inflammatory phenotype." (PMID 40764998, 2025). "FOXO1 has been widely reported to exert tumor-suppressive effects across diverse cancer types." (PMID 41369154, 2025). "GlcN also increased the expression of FoxO1 and FoxO3, known tumor suppressors in various cancers." (PMID 39816727, 2025). "However, developing PAX7::FOXO1 tumor models would allow for comparative analyses to identify mechanisms responsible for disease aggressiveness." (PMID 38916046, 2024). "We observed that FoxO1 expression was upregulated in FBXO22‐knockdown xenograft tumour tissues." (PMID 39153212, 2024). "Paradoxically, several studies have reported that FOXO1 supports tumor growth." (PMID 38519029, 2024). "Notably, FOXO1 activity correlated with positive clinical outcomes of patients treated with CAR T cells or tumour-infiltrating lymphocytes, underscoring the clinical relevance of FOXO1 in cancer immunotherapy." (PMID 38600391, 2024). "Although the precise mechanism through which MLIP increases FOXO-1 expression remains unknown, FOXO-1 is acknowledged for its involvement in cell cycle arrest, apoptosis, and tumor suppression, implying a potential role for MLIP in cancer pathogenesis." (PMID 38994962, 2024).
tumor (continued). "Furthermore, upon treating various types of tumour cell lines with FOXO1 inhibitors, we observed not only the upregulation of VEGFC, PD‐L1 and CCL4 but also varying degrees of increase in MOMP‐related molecules (such as BAX, BAK1, CASP3, STING, IRF3 and RELB)." (PMID 38899748, 2024). "Paradoxically, FOXO1 may also promote tumourigenesis by directly upregulating the transcription of VEGFC, which is intricately linked with tumour progression and metastasis." (PMID 38899748, 2024). "This was associated with increased tumour infiltration of FOXO1-expressing human CAR T cells and without overt signs of toxicity, supporting the safety and potential clinical applicability of this approach." (PMID 38600376, 2024). "Moreover, the inactivation of HOXB2 or activation of FOXO1 are potential strategies to inhibit tumor progression and overcome radioresistance in NPC." (PMID 38617001, 2024). "The tumor apoptotic effects exerted by TRAIL are also dependent on the FOXO1." (PMID 39516471, 2024). "But the OSanalysis result was consistent with the result from the TCGA database that theexpression of FOXO1 was significantly increased in tumor tissues, which indicatedthat FOXO1 might play a role of oncogenic gene in LGG." (PMID 38716982, 2024). "Additionally, the response of autophagy to cellular stress is pivotal, as evidenced by increased SIRT1 and FoxO1 levels under glucose deprivation in gastric cancer, which boosts Rab7 expression and autophagy, supporting tumor cell survival." (PMID 39403142, 2024). "Finally, when evaluated in an in vivo setting, FOXO1 overexpression improved CAR-T cell anti-tumour control in a range of preclinical solid tumour models, including murine breast carcinoma and colon adenocarcinoma, and human ovarian cancer and osteosarcoma." (PMID 39399500, 2024). "Interestingly, we found a decrease of the FOXO1 regulon activities in IM with H. pylori infection suggesting the inhibition of the tumor-suppressing process, consistent with the previous finding that FOXO1 can inhibit proliferation of GC cells." (PMID 38882015, 2024). "Although there is no direct evidence suggesting that FOXO1 regulates the radiation response of cancer cells, FOXO1 is still an important factor in cancer processes based on its inclusion in the oncogene and tumor suppressor gene list from the Cancer Gene Census project." (PMID 38406264, 2024). "However, we observed a switch in this phenotype after activation, whereby FOXO1-overexpressing CD8+ CAR T cells showed higher expression of glycolytic genes relative to control CAR T cells following co-culture with Lewis Y+ tumour cells." (PMID 38600376, 2024). "The results indicate that deleting Foxo1 failed to rescue the loss of the tumor-inhibitory effects of mTORC2." (PMID 39325536, 2024). "Collectively, our data infer that CAR T cell trafficking through tumour dLNs may be promoted through the overexpression of FOXO1-ADA and contributes to improved CAR T cell polyfunctionality." (PMID 38600376, 2024). "Knockout of FOXO1 significantly reduced CAR T cell tumour control and survival." (PMID 38600391, 2024). "Indeed, combination of FOXO1-ADA expressing CAR T cells with anti-PD-1 resulted in significantly improved tumour growth inhibition compared with control CAR T cells, suggesting synergy between FOXO1-ADA CAR T cells and PD-1 blockade." (PMID 38600376, 2024). "Immunophenotyping shows that the frequency of tumor-infiltrating Tregs was not increased in Foxo1fl/flCD4Cre+ mice in comparison to Foxo1fl/flCD4Cre− mice with Zn supplementation, suggesting that FOXO1 is essential for Zn-mediated Foxp3 Treg function in promoting tumor growth." (PMID 39247196, 2024). "The three proteins DLL1, FOXO1 and p27 were exclusively expressed by the T14 RB tumor cells." (PMID 39695086, 2024). "Additionally, circRPN2 acts as a ceRNA for miR-183-5p, increasing FOXO1 (Forkhead Box O1) expression, which blocks tumor progression and glucose metabolism." (PMID 38398157, 2024).
tumor (continued). "A previous study showed that FOXO1 (Forkhead Box O1) activation could inhibit the tumor growth and induce cell autophagy and cell death." (PMID 37065484, 2023). "The phosphorylated AKT (p-AKT) can activate multiple downstream signaling molecules, inhibit tumor cell autophagy through mTOR, phosphorylate MADD, caspase-3, caspase-9, phosphorylate FOXO-1 to control the cell cycle, and promote tumor cell growth and/or metastasis." (PMID 37070074, 2023). "It was previously reported that decreased FoxO1 expression could inhibit tumor formation, while an increase in its expression promoted tumor resistance to drugs." (PMID 37293593, 2023). "In addition, we have detected the FOXO1/TRIM15/LASP1/AKT loop in tumor samples from HCC patients with TKI sensitive or resistance." (PMID 36670097, 2023). "Similar to FOXO1, most studies agree on the tumor-suppressive feature of FOXO3." (PMID 37821870, 2023). "In accordance with these reports, we confirmed the anti-tumor effects of FoxO1 in HCC cells." (PMID 37099251, 2023). "Upstream regulator analysis comparing RNA sequencing data from PKM2KO and PKM2WT T cells isolated back from mouse tumors after adoptive co-transfers and from AG1 and DMSO treated T cells isolated after in vitro co-culture with tumor cells demonstrated conserved Foxo1 and Bach2 signatures." (PMID 37790365, 2023). "FOXOs have traditionally been regarded as tumour suppressors not only due to their canonical activity being associated with detrimental cellular fate (e.g. cell cycle arrest and apoptosis), but also due to deletion of FOXO1/3/4 in adult mice leading to tumour formation." (PMID 37275916, 2023). "FOXO1 positivity rates across different tumour sizes were equal (p = 0.544)." (PMID 37138963, 2023). "Moreover, venetoclax (BCL2i)-resistant FL cells exhibit increased levels of p-FOXO1/p-FOXO3 associated with diminished BIM activity, thereby preventing cell death supporting the role of FOXO family members as tumour suppressors in FL." (PMID 37275916, 2023). "In addition, knockdown of HMGB1 and FOXO1 simultaneously restored the changes in the tumor size, volume and fluorescence intensity in mice induced by circHERC1 overexpression." (PMID 37932766, 2023). "FOXO1 is a major tumor suppressor which controls cell proliferation." (PMID 36835085, 2023). "Conversely, EWS-FLI1 reduces the expression of genes involved in tumor suppressor mechanism (ex: apoptosis), such as FOXO1 (Forkhead Box O1), or IER3 (Immediate Early Response 3), tumor suppressor genes regulating mechanisms such as DNA repair, cell cycle arrest and apoptosis." (PMID 37752913, 2023). "As the association between the transcriptional activation of a major tumor suppressor gene, FoxO3, and ATP1A1 signaling has been established, we proceed to explore the association of the ATP1A1 and the pro-autophagic gene, FoxO1 in MASH-HCC." (PMID 37830582, 2023). "FOXO1-positive tumours did have an inferior survival but this association was not significant on univariate analysis." (PMID 37138963, 2023). "In addition, FoxO1 is known to have reduced expression and to function as a tumor suppressor in HCC." (PMID 37099251, 2023). "Moreover, bioinformatics analysis evidenced the tumor-suppressors Cyld and Foxo1 as putative miR-182-5p target genes." (PMID 37298191, 2023). "We hypothesize that intrinsic expression of CTLA-4, PDCD1 (PD1), CD274 (PD-L1), PDCD1LG2 (PD-L2), CD276 (B7-H3), JAK2, and FoXO1 in neoplastic cells depends on BC immunophenotype, stem cell properties, and tumor microenvironment." (PMID 36901916, 2023). "In GC, phosphorylated FoxO1 plays an important role in tumor angiogenesis." (PMID 37293593, 2023). "In patients with FOXO1 fusion data available (Cohort 3), while nodal status and site of primary tumour impacted EFS and OS on univariate analysis, primary tumour size was the strongest prognostic variable on both univariate and multivariate analysis impacting both EFS and OS." (PMID 37138963, 2023).